NDUFB5 (NADH:ubiquinone oxidoreductase subunit B5)
Description:
Accessory subunit of the mitochondrial membrane respiratory chain NADH dehydrogenase (Complex I), that is believed not to be involved in catalysis. Complex I functions in the transfer of electrons from NADH to the respiratory chain. The immediate electron acceptor for the enzyme is believed to be ubiquinone.
Synonyms: CI-SGDH; SGDH; MGC12314; CISGDH
Tractability: Small molecule: an approved drug acts on it; a structure with a bound ligand is known. Antibody: UniProt predicts a signal peptide or a membrane-spanning region. PROTAC: ubiquitination databases record sites on it; its protein half-life has been measured.
Target class: Enzyme; Oxidoreductase
Gene: Protein-coding gene on chromosome 3 (179,604,690 to 179,627,647, forward strand). Ensembl gene ENSG00000136521.
Subcellular location: Mitochondrion inner membrane
Subcellular location (Human Protein Atlas): Mitochondria; Nucleoplasm
Pathways (Reactome):
Metabolism: Complex I biogenesis; Respiratory electron transport
Gene Ontology:
Molecular function: protein binding; NADH dehydrogenase (ubiquinone) activity
Biological process: aerobic respiration; mitochondrial electron transport, NADH to ubiquinone; proton motive force-driven mitochondrial ATP synthesis; proton transmembrane transport
Cellular component: mitochondrial inner membrane; mitochondrion; respiratory chain complex I
Genetic constraint (gnomAD): Loss-of-function variants: 10 observed, 10.69 expected, observed/expected ratio (o/e) 0.94, 90% interval 0.58 to 1.57. The upper end of that interval is the gene's LOEUF score, 1.57, which puts it in group 6 of 6, group 1 being the genes least tolerant of losing a copy. Missense variants: 158 observed, 157.2 expected, observed/expected ratio (o/e) 1.01, 90% interval 0.88 to 1.15. Synonymous variants: 55 observed, 59.52 expected, observed/expected ratio (o/e) 0.92, 90% interval 0.74 to 1.16.
Homologues: Orthologues: chimpanzee NDUFB5 (100% identical), macaque NDUFB5 (92% identical), rabbit NDUFB5 (84% identical), pig NDUFB5 (83% identical), guinea pig NDUFB5 (83% identical), dog NDUFB5 (82% identical), rat Ndufb5 (76% identical), mouse Ndufb5 (76% identical), tropical clawed frog ndufb5 (62% identical), zebrafish ndufb5 (54% identical), Drosophila melanogaster ND-SGDH (36% identical), Caenorhabditis elegans ndub-5 (23% identical).
Diseases named in the same sentence as NDUFB5 in open-access papers:
NDUFB5 is named in the same sentence as 21 diseases in open-access papers, as found by Europe PMC text mining. Sharing a sentence is not in itself a finding about the gene and the disease. The quoted sentences say what the papers report.
Parkinson disease (2 papers, 2017 to 2022). A progressive degenerative disorder of the central nervous system characterized by loss of dopamine producing neurons in the substantia nigra and the presence of Lewy bodies in the substantia nigra and locus coeruleus. "Parkinson’s disease is a pathway specifically associated to diseases of the central nervous system, NDUFB5 and SLC18A1 are enriched in this pathway." (PMID 29170526, 2017).
cognitive decline (1 paper, 2021). "Overlapping the proteins consistent in both AD datasets with data from transgenic mice revealed four novel, high-confidence candidates that were associated with cognitive decline and drug-mediated multi-target kinase inhibition: PACSIN1, GJA1, VSNL1 and NDUFB5." (PMID 33530349, 2021).
Kabuki syndrome (1 paper, 2024). Kabuki syndrome (KS) is a multiple congenital anomaly syndrome characterized by typical facial features, skeletal anomalies, mild to moderate intellectual disability and postnatal growth deficiency. "NDUFB5 encodes a subunit of complex I, which plays a role in oxidative phosphorylation, a pathway known to be dysregulated in KMT2D-deficient lung adenocarcinomas and Kabuki syndrome patients." (PMID 39578878, 2024).
ovarian carcinoma (1 paper, 2024). A malignant neoplasm originating from the surface ovarian epithelium. "The results presented in this manuscript reveal that the treatment of ovarian cancer cells with RuCN induced a higher content of α-helices and a lower content of β-sheet structures compared to the untreated control and the overexpression of NDUFA1 and NDUFB5, respectively." (PMID 39204341, 2024).
cancer (2 papers, 2014 to 2024). A tumor composed of atypical neoplastic, often pleomorphic cells that invade other tissues. "We highlighted cancer type-specific genetic interactors, namely NDUFB5, MDM2, TUBA1B, and WRN, which were promising targets of existing and in-development drugs." (PMID 39578878, 2024). "We identified three priority class A candidates—namely the SL interactors MDM2, TUBA1B (COAD/READ), and NDUFB5 (STAD) and the AL interactor CDK6 (in the pan-cancer dataset)—that encode targets of approved anticancer drugs or that are the focus of drug development efforts." (PMID 39578878, 2024). "Furthermore, results from the in silico GI screens identified several SL candidates—namely NDUFB5 (in the STAD screen), MDM2 and TUBA1B (in the COAD/READ screen), and WRN (in the pan-cancer and COAD/READ screens)—which encode proteins that can be inhibited using existing and in-development drugs." (PMID 39578878, 2024).
mitochondrial disease (1 paper, 2021). "Many mitochondrial disease-related altered proteins also formed part of the energy network (DLD, NDUFA4, NDUFB5, NDUFB6, NDUFB9, NDUFS1, NDUFA12 and UQCRB) and belong to respiratory electron transport with the exception of DLD, which belongs to the TCA cycle." (PMID 34576238, 2021).
tumours (1 paper, 2021). "Specifically, four genes (RN7SK, TNFRSF11B, NDUFB5 and RARRES3) were shown to be progressively up-regulated in primary and recurrent tumours compared to normal." (PMID 34062972, 2021).
NDUFB5 also shares sentences with these, for which no sentence is quoted: Alzheimer disease (2 papers); breast carcinoma (1); depressive disorder (1); diabetic foot ulcer (1); diseases of the central nervous system (1); Huntington disease (1); lipid metabolism disorders (1); lung adenocarcinoma (1); neurodegenerative disease (1); neurodevelopmental disorder (1); Neurological Disorder (1); sarcopenia (1); steatosis (1); type 2 diabetic (1).